FGFR1 (fibroblast growth factor receptor 1)
Diseases named in the same sentence as FGFR1 in open-access papers (continued):
Sharing a sentence is not in itself a finding about the gene and the disease.
breast cancer (continued). "It has also been shown that HER2 expression in breast cancer cells upregulates FGF2 and FGFR1, which promotes EMT and resistance to Lapatinib." (PMID 30111373, 2018). "Understanding the process of amplicon formation, an example of which we present here for the chr8:ZNF703/FGFR1 and chr11:CCND1 co-amplifications, will be important for our understanding of the origins of a subset of breast cancers." (PMID 30252041, 2018). "It is possible that activation of FGFR1 activates the endogenous Ras proteins in DCIS.COM cells, which cooperate with mutant H-Ras to promote breast cancer cell proliferation, and progression." (PMID 30111373, 2018). "To gauge the confounding nature of commonly amplified genes in breast cancer, we further performed multivariate analysis on the candidate genes with cases of amplification of MYC, FGFR1, CCND1, and ERBB2." (PMID 30181556, 2018). "HSPGs are known to control invasion of breast cancer cells; particularly syndecan 1 and 4, upregulate the formation of FGF-2/HSPG/FGFR-1 invasion complex in MCF7 breast cancer cells." (PMID 29566097, 2018). "The chr8:ZNF703/FGFR1 and chr11:CCND1 amplifications are amongst the most frequent in breast cancer, particularly in ER-positive breast tumours (19% and 28%, respectively, of amplifications in ER-positive tumours; 11% and 16%, respectively, of total cohort)." (PMID 30252041, 2018). "Amplifications in FGFR1 and FGFR4 are found in 9% to 10% and 10% of primary breast cancers overall, respectively." (PMID 28183331, 2017). "Dovitinib (TKI258), a small-molecule inhibitor of FGFR1, FGFR2, and FGFR3 and other receptor tyrosine kinases, has shown preclinical activity in FGFR-expressing breast cancer models in vivo and in vitro." (PMID 28183331, 2017). "More specifically, TGFBR1 and FGFR1 in combination with highly expressed E2F1 induce the most invasive phenotype in bladder cancer, whereas in breast cancer, it is the combined action of TGFBR2, EGFR, and E2F1 that triggers high levels of invasiveness." (PMID 28775339, 2017). "Aberrant PI3K/Akt/mTOR signaling is also seen in cells with FGFR1 overexpression and amplification, and response to the PI3K inhibitor alpelisib is reduced in ER+/PIK3CA-mutant breast cancer cells that overexpress FGFR1." (PMID 28183331, 2017). "Genes with recurrent amplifications in breast cancer showed 100% (ERBB2, FGFR1), 96% (CCND1), and 88% (MYC) concordance for the amplified/non-amplified status." (PMID 27028851, 2016). "We then focused the comparison of CNAs on known driver oncogenes located within regions frequently amplified in breast cancer: ERBB2 (17q12), CCND1 (11q13.3), FGFR1 (8p11.23), MYC (8q24), and PAK1 (11q14.1)." (PMID 27028851, 2016). "FGFR1 was shown to be amplified in breast cancer and lung cancer, FGFR2 in breast cancer and gastric cancer." (PMID 27409346, 2016). "At the gene levels, genes with recurrent amplifications in breast cancer showed different degrees of concordance: 100% for ERBB2 and FGFR1, 96% for CCND1, but 88% for MYC, suggesting possible differences for driver genes." (PMID 27028851, 2016). "In a phase II clinical trial (NCT01795768), AZD4547 showed therapeutic efficacy as a second-line treatment in patients with FGFR1- and FGFR2-amplified breast cancer, squamous cell carcinoma of the lung, or gastro-esophageal adenocarcinoma." (PMID 26555375, 2015). "Comparing these FGFR1 levels with those in normal cells, we observed a significant increase in MG63 (~3-fold) and up-regulation in all 3 breast cancer lines." (PMID 26201468, 2015). "While FGFR1 alone resulted in very few palpable tumors with a long latency, FGFR1 is often amplified with other oncogenes such as c-MYC and CCND1 in breast cancer, which are downstream targets of the canonical Wnt signaling pathway." (PMID 26581390, 2015).
breast cancer (continued). "ZNF703, like FGFR1, is localized at the 8p11 locus and there is compelling evidence that ZNF703 is one of the driver genes in this amplified region, especially in breast cancers where ZNF703 expression seems to be induced by estrogens." (PMID 25596748, 2015). "We also show that when overexpressed in S115 cells or added to the culture medium of either S115 or human MCF-7 breast cancer cells, FGF-8b increased FGFR1 expression." (PMID 23185502, 2012). "Other genes, like epidermal growth factor receptor (EGFR), Fibroblast growth factor receptor 1 (FGFR1), topoisomerase IIa (TOP2A) and MYC are also involved in female breast cancer and have prognostic and therapeutic implications." (PMID 22527098, 2012). "This subset included known breast cancer genes, like EGFR (7p11), FGFR1 (8p12), ERBB2 (17q12), PPM1D (17q23) and ZNF217 (20q13)." (PMID 19582160, 2009). "Increased levels of FGF10 are observed in ~10% of human breast cancers, and amplification and overexpression of several FGFRs, including FGFR1, FGFR2, and FGFR4, have been observed in breast cancers." (PMID 16933995, 2006). "In context with FGFR1 overexpression-mediated activation of Akt and Erk1/2, these data demonstrate that FGFR1-induced ERα phosphorylation and crosstalk between RTK-ER pathways are key mechanisms of alpelisib resistance in breast cancer cells." (PMID 40510030, 2025). "Breast cancer harbors FGFR aberrations in 14–18% of cases, predominantly FGFR1 amplifications." (PMID 41514604, 2025). "To date, several selective FGFR inhibitors have been tested in clinical trials in patients with ER+ breast cancer harboring FGFR1 amplification, but sensitivity to FGFR inhibitors has not been determined by FGFR1 amplification." (PMID 40227585, 2025). "We previously demonstrated that FGFR1 serves as a negative prognostic marker in luminal A breast cancer." (PMID 40510030, 2025). "Amplifications of RTKs such as EGFR (epidermal growth factor receptor) and FGFR1 (fibroblast growth factor receptor 1) are frequently observed in breast cancers that do not respond to ET." (PMID 40244377, 2025). "Another noteworthy finding in our study is the inverse growth stimulatory and inhibitory effects FGFR inhibitors have in FGFR1 amplified and non-amplified ER + breast cancer cells." (PMID 38553760, 2024). "By comparing their impact on two subsets of ER + breast cancer cell lines—one with FGFR1 amplification (CAMA1, MDA-MB-134) and the other without (MCF7, T47D)—we confirmed contradictory growth effects and investigated underlying mechanisms." (PMID 38553760, 2024). "We studied the effects of FGF2 treatment on proliferation using 3D spheroids of ER + breast cancer cell lines with FGFR1 amplification (CAMA1, MDA-MB-134) and those without (MCF7, T47D)." (PMID 38553760, 2024). "Our study demonstrated the ability of FGF ligands to stimulate cell proliferation and spheroid growth in ER + breast cancer cell lines without FGFR1 amplification (MCF7, T47D), a phenomenon widely recognized." (PMID 38553760, 2024). "The genomic analysis of The Cancer Genome Atlas (TCGA) and the Molecular Taxonomy of Breast Cancer International Consortium (METABRIC) databases confirmed that the amplification of FGFR1 is the most common type of FGFR alteration, occurring in nearly 14% of patients with breast cancer." (PMID 38255923, 2024). "In breast cancer cells with FGFR1 amplification (CAMA1 and MDA-MB-134), FGF2 elevated non-canonical FGFR downstream signaling pathways, especially JAK-STAT pathway, to promote p21 expression and modulate the ratio of p21/CCND1 to drive cell cycle arrest." (PMID 38553760, 2024).
breast cancer (continued). "Although our studies are supported by findings in other cancers where FGFR1 upregulation has been observed after BET inhibition, such as uveal melanoma, breast cancer, or ovarian cancer cells, we are the first to demonstrate that this is an early event in the intrinsic resistance mechanism." (PMID 38654040, 2024). "Ultimately, our results support the hypothesis that FGFR1 level regulates the cell cycle and stemness status in response to FGF2 stimulation in breast cancer cells." (PMID 38553760, 2024). "Additionally, multivalent conjugates, such as bispecific ADCs like AfHER2-lFGF2-vcMMAE, target both FGFR1 and HER2 in breast cancer, offering a promising new treatment approach." (PMID 39796710, 2024). "There is a direct binding interaction between FGFR1 and MD2 in breast cancer cells." (PMID 37490511, 2023). "Our study showed that CAPE could inhibit the phosphorylation of FGFR1, restrain FGFR1 nuclear transfer, and eventually block the EMT process as well as the migration and invasion of breast cancer cells." (PMID 37490511, 2023). "FGFR1 overexpression and activation also upregulate ZEB-1 to promote EMT and EGFR inhibitor resistance in NSCLC cells 18, and increase the release of inflammatory chemokines such as CXCL1/5 to promote mammary tumor growth and progression." (PMID 36778115, 2023). "Importantly, we previously developed a monomeric FGF2-based conjugate that exhibited high toxicity against FGFR1-overproducing cancer cells in vitro and showed efficient tumor growth retardation in an FGFR-positive human breast cancer xenograft model in mice." (PMID 37373291, 2023). "Moreover, recent studies have revealed that FGFR1 acquires resistance to lapatinib, trastuzumab, and TDM-1 in breast cancer." (PMID 38054134, 2023). "Lucitanib strongly inhibits FGFR1, FGFR2, and VEGFR1–3, and it has antiangiogenic and broad‐spectrum antitumor activity against several cancers, including small cell lung cancer, breast cancer, nasopharyngeal carcinoma, colorectal cancer, ovarian cancer, and kidney cancer." (PMID 37750089, 2023). "Our study identified FGFR1 as the target of miR-4687-5p, which was previously reported to be downregulated in ALS (amyotrophic lateral sclerosis), cystic echinococcosis, polycystic ovary syndrome, and breast cancer." (PMID 37993879, 2023). "In this study, we found that activation of the FGFR1 signaling enhances the phosphorylation of both ERK1 and ERK2, and inhibition of MEK to prevent the activation of both ERK1 and ERK2 blocked the FGFR1 signaling-induced FOXQ1 upregulation and breast cancer cell proliferation." (PMID 36778115, 2023). "12b was demonstrated to bind to TfR1 directly and cause iron deprivation as well as dysregulation of the intracellular oxidative environment, in turn inducing degradation of FGFR1 oncoprotein through proteasome pathway and TfR1-related cell apoptosis in MDA-MB-231 breast cancer cells." (PMID 35624697, 2022). "RNAscope is a technique that can determine overexpression of mRNA in paraffinized samples and has a standardized quantitation method; FGFR1 has not been previously studied in breast cancer by this method." (PMID 33579347, 2021). "Single-agent FGFR1-inhibitors do not show sufficiently high activity in advanced HR+ breast cancer to warrant further development." (PMID 33579347, 2021).
breast cancer (continued). "The correlation between amplification and overexpression and the prognostic/predictive role of overexpression of FGFR1 are less clear than those for that human epidermal growth factor 2 (HER2), which is amplified or overexpressed in a similar number of breast cancer cases." (PMID 33579347, 2021). "Lucitanib (E3810 or AL3810) is a reversible, ATP‐competitive TKI that targets FGFR1‐2 and VEGFR1‐3 in the nM range and exerts antitumour activity in multiple preclinical models, including colon, ovarian, renal and thyroid carcinoma and breast cancer." (PMID 33655556, 2021). "With the current number of available options for advanced HR+ breast cancer, the development of FGFR inhibitors will be challenging unless a biomarker that narrows down the population that will benefit from FGFR1 blockade and a specific therapeutic niche are determined." (PMID 33579347, 2021). "Additionally, an ER- breast cancer cell line was shown to maintain paracrine loop signaling from 17β-estradiol and induce the upregulation and secretion of FGF2 and increase FGFR1 signaling." (PMID 33019728, 2020). "Patients with contralateral breast cancer, breast cancer with distant metastasis at diagnosis, missing FGFR1 data, and those without a positive observation time were excluded (n = 391), resulting in a final sample size of 503 patients." (PMID 32852708, 2020). "For instance, it has been shown that the functional interplay linking the activation of FGFR1 in epithelial cells to the chemokine expression in macrophages (i.e., CXCL1 and CXCL5) may lead to mammary tumor formation and progression." (PMID 33081025, 2020). "Patients with breast cancer who had normal FGFR1 copy numbers showed lower expression rate measurements (IHC) for the estrogen receptor (median, 70%; IQR, 10% to 80%) than patients with FGFR1 amplification (median, 80%; IQR, 60% to 90%)." (PMID 32852708, 2020). "Breast cancer patients with FGFR1 amplification had a poorer DMFS than patients without amplification (P = 0.04, unadjusted analysis); however, this difference in DMFS outcome did not achieve significance in the adjusted analysis (P = 0.05)." (PMID 32852708, 2020). "Regarding therapy of breast cancers harboring the 8p11.23 amplicon, FGFR inhibitors have been investigated and could be a rational targeted therapy for cancers overexpressing FGFR1." (PMID 32987805, 2020). "De novo amplification of FGFR1 has also been detected in a metastatic deposit of breast cancer (BC) patients not present in the primary tumor." (PMID 32517171, 2020). "Hence, we analyzed the mRNA levels of FGFR1 and CTGF in METABRIC breast cancer patients database and we found a positive correlation between FGFR1 and CTGF expression." (PMID 30866584, 2019). "There is amplification of FGFR1 and FGFR2 in ER+ breast cancer and TNBC, respectively, and FGFR1 amplification was noted as an independent factor to predict the overall survival in ER + breast cancer." (PMID 31754359, 2019). "Here, the authors show that FGFR1 amplification is a resistance mechanism to CDK4/6 inhibitor and endocrine therapy and that combined treatment with FGFR, CDK4/6, and anti-estrogens is a potential therapeutic strategy in Era+ breast cancer tumors." (PMID 30914635, 2019). "Although our study has characterized the pathological role of alternative FGFR1 splicing in breast cancer, further study is needed to determin if the FGFR isoforms can assist in idenfifying patients with FGFR-driven breast cancers and help therapeutic decision making." (PMID 30713601, 2019). "Thus, the regulatory relationship between FGFR1 and MMP-1 downstream to miR-361-5p in breast cancer remains to be investigated in the future." (PMID 29132384, 2017). "Overexpression of fibroblast growth factor receptor 1 (FGFR1), found in ≤8% of hormone receptor–positive (HR+), human epidermal growth factor receptor 2–negative (HER2−) breast cancer cases, is correlated with decreased overall survival and resistance to endocrine therapy (ET)." (PMID 28183331, 2017).
breast cancer (continued). "Breast cancer patients with FGFR1 amplification also had worse overall survival (median survival, 48.1 months) than patients without FGFR1 amplification (median survival, 104.9 months; p < 0.01)." (PMID 28125801, 2017). "Moreover, the concentrations at which sorafenib inhibits FGFR1 autocrine activation in MPM TICs are similar to those reported to affect the RAF/MEK/ERK pathway and activated RTK in human breast cancer cell lines." (PMID 28545562, 2017). "Our results indicate that miR-361-5p inhibits breast cancer cells glycolysis and invasion by respectively repressing FGFR1 and MMP-1, suggesting that miR-361-5p and its targets may serve as therapeutic targets in breast cancer treatment." (PMID 29132384, 2017). "FGFR3 and FGFR4 amplification are less common than FGFR1 and FGFR2 in breast cancer." (PMID 27489863, 2016). "As negative controls, we also included the H2228 human lung cancer and T47D human breast cancer cell lines which show low or no expression of FGFR1-4." (PMID 27391347, 2016). "Together with the current findings, we postulated that FGFR1 expression could regulate SOX2 expression and subsequently neuroendocrine differentiation in breast cancer." (PMID 26673008, 2016). "Overall, unconfirmed response or stable disease for more than 6 months was observed in 5 (25 %) and 1 (3 %) patient(s) with FGFR1-amplified and FGFR1-nonamplified breast cancers, respectively." (PMID 26059247, 2015). "However, of this group of genes, only FGFR1 and DDHD2 were shown to function as oncogenes in breast cancer, and DDHD2 was shown to have transforming potential that was not dependent on FGFR1 expression." (PMID 25653011, 2015). "Downregulation of FGFR1 signaling in the established Wnt1/iR1 mammary tumors resulted in rapid regression to a nonpalpable state." (PMID 26581390, 2015). "Nevertheless, FGFR1 and its downstream regulatory proteins on breast cancer cells were not affected by formononetin." (PMID 26575424, 2015). "Subgroup analyses also revealed a difference in survival between the patients with and without FGFR1-amplified breast cancer in the hormone receptor-positive group (P = 0.001), but not in the hormone receptor-negative group (P = 0.284)." (PMID 22863309, 2012). "The HER2, C-MYC, CCND1 and FGFR1 amplification status was in most cases concordant in the matched invasive and DCIS components of the same tumors, pointing to early roles in the development of breast cancer." (PMID 22863309, 2012). "In Kaplan-Meier survival analyses, the patients with FGFR1-amplified breast cancer had shorter disease-free survival times than those without it (P = 0.003)." (PMID 22863309, 2012). "Among the low and intermediate grade breast cancers, the FGFR-1 negative tumors were resistant to chemoradiotherapy." (PMID 23270564, 2012). "Although FGFR1 is not widely accepted as the driver breast cancer oncogene affected in the 8p11-12 amplification, its amplification has been reported to be associated with poor prognosis, especially in patients with ER-positive tumors." (PMID 22863309, 2012). "Most of studies did not encounter the lobular subtypes of breast carcinoma when evaluating FGFR-1 gene status." (PMID 23270564, 2012). "One-third of these loci affected breast cancer oncogenes, whose amplifications were validated with specific probes: 17q12 (two cell lines with ERBB2 amplifications), 11q13 (two with cyclin-D1), 8p11–p12 (two with FGFR1) and 10q25 (one with FGFR2)." (PMID 10604729, 1999). "To test if the role of FGF2 could shift from promoting proliferation to inducing a stem-like state in FGFR1 amplified cells, we next investigated the effect of FGF2 on cancer stemness-like traits using FACS analysis for ALDH and CD44 (two known markers of breast cancer stemness)." (PMID 38553760, 2024).